TNF (tumor necrosis factor)
Diseases named in the same sentence as TNF in open-access papers (continued):
Sharing a sentence is not in itself a finding about the gene and the disease.
neuropathy (continued). "Total calcium, tumor necrosis factor-α (TNF-α), interleukin-6 (IL-6), interleukin-10 (IL-10), myeloperoxidase, and severe neurodegeneration were also examined, as they were strongly associated with VCR-induced neuropathy in animal models." (PMID 37107178, 2023). "Furthermore, the blockage of TNF-α signaling using either TNF-α knockout mice or anti-TNF-α monoclonal antibody improved neuropathy in diabetic mice." (PMID 36946851, 2023). "The pathogenesis of UP may involve inflammatory states, such as increased levels of pro-inflammatory cytokines (IL-6, IL-2, and TNF-α), immune changes, and neuropathy." (PMID 37675019, 2022). "Nerves from group 2 (TNF) show clear evidence of TNF induced neuropathy (Figures 4A3,4)." (PMID 36159399, 2022). "Importantly, inhibition of TNF-α or IL-1 signaling in a rat model of paclitaxel-induced neuropathy was able to attenuate mechanical and cold hypersensitivity." (PMID 35250568, 2022). "Particularly, increased levels of IL-1β, IL-6 and TNF-α in ALS patients compared to controls or patients with other neuropathies have been reported, suggesting that the modulation of these inflammatory mediators may ameliorate the course of the disease." (PMID 36362341, 2022). "Corroborating our findings, it has also been shown that animals submitted to partial sciatic nerve ligation and 10-day oral supplementation of concentrated fish oil had lower concentrations of TNF in the spinal cord when compared to vehicle-treated mice 9 days after neuropathy induction." (PMID 35431823, 2022). "In our previous study, we observed that irisin gene delivery ameliorated burn-induced sensory and motor neuropathy by reducing tumor necrosis factor α–induced neuronal apoptosis, which indicates that irisin has antineurodegenerative effects on burn-induced neuropathy." (PMID 36555538, 2022). "Thus, it is assumed that stress increases TNF‐α and, possibly to a lesser extent, IL‐1β levels in the PFC and can cause neuropathy, but BHB suppresses neuroinflammation and exerts a neuroprotective effect." (PMID 32125791, 2020). "The current report also supports the possible involvement of other complimentary cytokines such as TNFα, in which it has been shown to be upregulated by IL-1β, can act synergistically with IL-1β during neuropathy and is involved in the induction and maintenance of allodynia." (PMID 30961664, 2019). "Our results revealed that the protective effect of OT in cisplatin-induced neuropathy may be due to its suppression on TNF-α production, lipid peroxidation, and elevation of antioxidant capacity." (PMID 25688351, 2015). "Indeed, human studies have suggested that anti-TNF-α drugs ameliorate neuropathic pain and neuropathy in Sjögren's syndrome, sciatica and disc-herniation." (PMID 24642694, 2014). "We therefore hypothesized that TNF-α may be a suitable therapeutic target for the treatment of neuropathic pain and neuropathy." (PMID 24642694, 2014). "Anti TNF agents have been reported in successful treatment of neuropathy in RA." (PMID 18973686, 2008). "All treatments were able to down-regulate the expression of TNF-α and IL-6, up-regulate the expression of TGF-β, rapidly improve hyperalgesia, grip strength, motor coordination, and nerve conduction velocity in rats with streptozotocin (STZ)-induced neuropathy, and improve neuropathy caused by T1D." (PMID 37175774, 2023). "A previous study has demonstrated that chemotherapy-induced neuropathy is associated with the induction of proinflammation mediators (such as IL-1β and TNF-α) in the dorsal root ganglion (DRG), which may ultimately cause the initiation and maintenance of persistent neuropathy." (PMID 34366713, 2021). "TNFα is an inflammatory factor that may complicate neuropathy." (PMID 33096842, 2020).
neuropathy (continued). "Additionally, inflammatory mediators have been shown to differentiate between painful- from painless-neuropathies of various etiologies, including elevated serum IL-2, TNF-α, and reduced anti-inflammatory IL-10; IL-6 and IL-10 sural nerve biopsy expression; and TNF-α in human Schwann cells." (PMID 31065863, 2019). "The role of spinal TNF-α has previously been shown to participate in the development of allodynia in a rat model of local spinal glial activation, and thus, may be an important consideration in PAE generating susceptibility to neuropathy." (PMID 30961664, 2019). "Strikingly, anti-TNF medication can even sporadically induce demyelinating diseases and neuropathies (cf. Section 4.3.4), and several groups found that TNF expressed in lymphoid organs could dampen the immune response by inhibiting the development of encephalitogenic T cells responses." (PMID 29751683, 2018). "Similarly, evidence has been accumulating indicating that inhibition of TNF-α could reduce inflammatory demyelination in various neuropathies, and TNF-α-knockout mice exhibit nerve preservation after WD induction." (PMID 23469058, 2013). "Therefore, we chose IVIg therapy because the symptoms of MAG-related neuropathy may be exacerbated by anti-TNF-α therapy." (PMID 23286283, 2013). "The suppression of PTX-induced neuropathy by BMX-001 occurs via inhibition of neuroinflammation in the dorsal horn of spinal cord due to reduced number of microglia and levels of TNF-α." (PMID 40900760, 2025). "The results of animal experiments indicated that elevated serum TNFα expression in DPN rats and elevated sciatic nerve IL-6 and IL-1β levels in diabetic rats were associated with neuropathy, this suggests that inflammatory factors may play a role in the pathogenesis of neuropathy." (PMID 39193373, 2024). "Sciatic nerve injury in a rodent model of neuropathy upregulates P2X4R expression in spinal microglia leading to increased production of IL-1β, TNFα and IL-6." (PMID 37166584, 2023). "It is likely that the amount of endogenous TLR4 ligands, like high mobility group box1 (HMGB1), is increased in painful neuropathy, binding to TLR4 and leading to the activation of the NF-κB pro-inflammatory cascade and the upregulation of TNFα." (PMID 37175520, 2023). "In other studies, increased expression of TNF-α and the phosphorylated form of JNK1/2 in the DRG of rats with bortezomib-induced neuropathy have been observed." (PMID 34640602, 2021). "Mean values for IL-1β, TNF, TGF-β, and IL-17 cytokine concentrations were higher in the Group of leprosy neuropathy in combination with neural pain than in the other Groups." (PMID 32038662, 2020). "Moreover, the authors hypothesized that increased TNF-α levels caused the upregulation of heparanase (HSPE) expression, an endoglycosidase involved in the production of inflammatory cytokines, which was secondary to the development of the neuropathy." (PMID 33613570, 2020). "Severity of neuropathy (NSS, NDS scores, visual analogue scale), cutaneous microcirculation (MC) parameters and inflammatory markers (ILs, CRP, TNFα) were assessed before and after treatment." (PMID 32825324, 2020). "TNF-α, IL-1β and NF-κB levels in sciatic nerve of PSNL control rats were significantly increased (p < 0.05) after induction of neuropathy as compared to normal as well as sham control rats." (PMID 28694757, 2017). "We found that IL6, TNF, CXCL8, IL1B and ERK1/2 were the top genes in terms of the number of connections in platinum-induced neuropathy, suggesting either direct or indirect interactions with nervous tissue leading to CIPN after exposure to platinum compounds." (PMID 26269716, 2015). "Previously, higher levels of systemic TNFα- and IL-2-mRNA were reported in HIV-1-negative painful neuropathies when compared with painless neuropathies." (PMID 24512313, 2014).
neuropathy (continued). "Model of neuropathy induced by L5 ventral root transection (L5-VRT) accompanied with mechanical allodynia and thermal hyperalgesia increased immunoreactivity for TNFα and TNFR1 receptors in the ipsilateral DRG and bilaterally in the spinal cord DH." (PMID 22189061, 2011). "In another study, where the authors compared untreated MM patients and treated MM patients with/without neuropathy, the untreated group had the highest TNF‐α plasma levels." (PMID 41578688, 2026). "The aim of this study was to assess systemic levels of the proinflammatory cytokines TNF‐α and IL‐6 as well as the chemokine CCL2 in a cohort of MM patients and to relate this to the severity of neuropathy in our cohort, to contribute to closing this translational gap." (PMID 41578688, 2026). "In the context of neuropathy, up-regulation of COX-2, iNOS, TNF-α, and IL-1β via the NF-κB and MAPK signaling cascades induces the infiltration of inflammatory cells, including neutrophils and monocytes, into the sciatic nerve and spinal cord of neuropathic mice." (PMID 40703750, 2025). "This direct anti-TNF-α effect is partial as it suppresses neuropathy-induced TNF-α overexpression without affecting the basal expression of the cytokine." (PMID 39334307, 2024). "The meta-analysis indicates a consistent elevation in TNF-α levels in individuals with DPN compared to those without neuropathy." (PMID 38179375, 2023). "It is obvious from the plot that the overall effect is positive, demonstrating increased TNF-α levels in DPN patients compared to diabetic individuals without neuropathy." (PMID 38179375, 2023). "The rat model of neuropathy used in this study showed that RTX injections decreased the mechanical threshold for pain, upregulated TNF-α inflammation in the DRG, and upregulated expressions of HDGF, PI3K, p-Akt/Akt, TrkB, iNOS, and substance P in the spinal cord." (PMID 33727914, 2021). "The untreated group without neuropathy showed higher concentrations of TNF-α, Chitinase3, IL-6, and IL-10 than the other groups." (PMID 34640602, 2021). "Furthermore, the decrease in serum TNF-α and increase in serum soluble TNF receptors show a positive correlation with neuropathy recovery in those patients." (PMID 23304492, 2012). "These neuropathy molecules include CGRP(↓), substance P(↓) and BDNF(↑), neuropeptide Y(↑), galanin(↑) via glial activation, which in turn activates the TNFα, MCP-1 and TLR4 pathways." (PMID 21996269, 2011). "Patients with painful neuropathy had a two-fold increase in IL-2 and TNF, while patients with nonpainful neuropathy had significantly higher mRNA levels of IL-4 and IL-10." (PMID 21994811, 2010). "This discrepancy may be explained by using a smaller sample size, which was calculated based on the change in TNF alpha rather than the incidence of neuropathy as the primary outcome." (PMID 41164763, 2025). "Tumor necrosis factor-alpha (TNF-α) and growth factors are nonspecific markers of neuropathy." (PMID 40792338, 2025). "Although the patients of our cohort did not have clinical neuritis and most of them did not have reactional episodes, the presence of TNF-α in the serum may suggest that it plays a role in the pathogenesis of leprosy neuropathy." (PMID 38116016, 2023). "Furthermore, most of these neuropathies improved over a period of months after withdrawal of the TNF-α antagonist, with or without additional immunomodulatory treatment." (PMID 23469058, 2013). "A recent study investigated mRNA levels of proinflammatory cytokines interleukin-2 (IL-2) and tumor necrosis factor-alpha (TNF) as well as anti-inflammatory cytokines IL-4 and IL-10 among patients with painful neuropathy, nonpainful neuropathy and control participants." (PMID 21994811, 2010). "However, we did show a slight increase in expression (fold = 1.73) of TNF-α at the transcript level using genetic microarrays in treated MM patients with PN compared with patients before and during the treatment without symptoms of neuropathy." (PMID 34640602, 2021).
neuropathy (continued). "Likewise, the dose-related effects of anti-TNF-α therapy on neurotoxicity were also demonstrated in the BIPN rat model, in which the co-administration of an antibody against TNF-α was able to revert the neuropathic symptoms, although the development of the neuropathy was not prevented." (PMID 33613570, 2020).
Opportunistic infection (131 papers, 2007 to 2026). An infection that is caused by a pathogen that would generally not be able to cause an infection in a host with a normal immune system. "While methotrexate itself has immunosuppressive properties, the concurrent use of biologic agents such as adalimumab, a TNF-α inhibitor, significantly elevates the risk of opportunistic infections, including PCP." (PMID 40821168, 2025). "This case highlights the importance of distinguishing PCP from drug-induced lung toxicity, particularly in patients receiving tumor necrosis factor-α inhibitors like adalimumab, which significantly increase susceptibility to opportunistic infections." (PMID 40821168, 2025). "Biologic agents like tumor necrosis factor (TNF) inhibitors (including adalimumab) have been implicated in increasing the susceptibility to opportunistic infections like PCP, although the incidence remains low." (PMID 40821168, 2025). "While effective, TNF-α blockade can impair immune surveillance, increasing susceptibility to opportunistic infections and paradoxical immune dysregulation." (PMID 41287667, 2025). "The most prevalent adverse effects associated with TNF inhibitors are injection site reactions (ISRs), and they also increase the risk of opportunistic infections." (PMID 40979853, 2025). "It has been shown that the combination of anti-TNF-α agents and thiopurines has been associated in a real-life setting with an increased risk for serious and opportunistic infections compared to monotherapy with both agents." (PMID 39055880, 2024). "There has also been reluctance to use some biologics (i.e., TNF inhibitors) due to the potential risk of opportunistic infections." (PMID 37711607, 2023). "When using biologics, the risk of bacterial and opportunistic infections is greater, but this risk mainly concerns anti-tumor necrosis factor (TNF) agents, while ustekinumab and vedolizumab probably have a more favorable safety profile." (PMID 37701431, 2023). "While TNF-α monoclonal antibody therapies have demonstrated efficacy in treating Behçet's disease, patients receiving these treatments are at risk of opportunistic infections due to immunosuppression." (PMID 37940896, 2023). "It has been suggested that the duration of therapy is related to the risk of developing opportunistic infections, with the first year of anti-TNF-α therapy (and particularly the first few months) being associated with a higher risk." (PMID 35323234, 2022). "Although treatment of CD with TNFα monoclonal antibodies is beneficial, many patients are at risk for acquiring opportunistic infections, and the treatment efficacy of TNFα monoclonal antibodies typically decreases over time." (PMID 35585977, 2022). "The use of TNF-a inhibitors in HIV patients has been associated with an increased risk of opportunistic infections." (PMID 35203438, 2022). "Anti-TNF-α treatment has a wide-ranging impact on the immune system and can cause severe systemic side effects including malignancies or opportunistic infections." (PMID 35214083, 2022). "One of the major concerns of blocking the actions of TNF-α, although the risk is small, is the increased risk of serious opportunistic infection due to its immunosuppressant effect." (PMID 35720854, 2022). "Arguments in support for earlier withdrawal of anti-TNF, including significant cost savings, reduced risk of opportunistic infections, and other serious side effects, are in part negated by the high relapse rates from clinical studies quoted here." (PMID 34621712, 2021). "As anti-TNF therapy is linked to immune suppression, AEs such as opportunistic infections are of special interest for this drug class." (PMID 34122068, 2021). "Conventional therapies for IBD include corticosteroids, immunosuppressants and anti-tumor necrosis factor (TNF)-α antibodies, often correlated with a risk of opportunistic infections and dysplasias, with expensive consequences on health system management." (PMID 32668581, 2020).
Opportunistic infection (continued). "Increased rates of infection have been reported in patients receiving TNF-α inhibitors, with upper respiratory tract infections, pharyngitis and sinusitis, most commonly reported, as well as an increased risk of opportunistic infections." (PMID 33141869, 2020). "TNF scavengers, such as etanercept and infliximab are associated with increased risk for opportunistic infections, giving rise to concerns about their use in immunocompromised patients, such as MF." (PMID 29749399, 2018). "Recent data show that TB is the most common opportunistic infection associated to anti-TNF treatment (0.06%)." (PMID 28146077, 2017). "Although the therapy can be highly effective, TNF-α inhibitors are associated with an increased risk of opportunistic infections." (PMID 28086756, 2017). "Biologic DMARDs, especially anti-TNF agents, are a further risk factor for many opportunistic infections." (PMID 28146077, 2017). "Previous studies have reported that the use of tumor necrosis factor-α antagonists increased the risk of opportunistic infections and reactivation of latent bacterial infections." (PMID 28179019, 2017). "Use of conventional TNF blockers results in an elevated risk of reactivating latent infections such as Mycobacterium tuberculosis or viral hepatitis, or of developing opportunistic infections." (PMID 27428882, 2016). "Overall, it is known that those on anti-TNF medications are at higher risk of opportunistic infections and that Listeria tends to follow a more aggressive course in these patients." (PMID 27651962, 2016). "Biological agents (tumor necrosis factor-α and interleukin-1 antagonists) should be stopped preoperatively and held until 14 days after surgery to avoid the risk of opportunistic infections." (PMID 26273625, 2015). "It was reported that the combination of thiopurines and anti-TNF biologic agents increases the relative risk of serious and opportunistic infections." (PMID 25015328, 2014). "All anti-TNF-α agents have been associated with a variety of serious and “routine” opportunistic infections." (PMID 20606887, 2010). "A number of factors (chronic fever, increased TNF-α and IL-6 levels, opportunistic infections and other secondary causes) have been considered to contribute to fat loss in advanced disease; however, a direct link to viral replication has not been established." (PMID 20822522, 2010). "TNF-α blockers increase the risk of opportunistic infections in patients with RA, most frequently due to intracellular organisms." (PMID 18203761, 2009). "During periods of inflammation caused by HIV-1 infection, co-pathogens, or opportunistic infections, levels of circulating cytokines such as IL-6 and TNFα increase and stimulate HIV-1 replication in monocytic cells." (PMID 20030845, 2009). "Immunotherapies can lead to significant adverse effects, particularly immunosuppression, which may elevate the risk of opportunistic infections, as evidenced by studies linking TNF-α inhibitors with increased susceptibility to infections." (PMID 40564149, 2025). "Although both upadacitinib and TNF-α inhibitors may increase the risk of opportunistic infections through immunosuppression, their specific molecular targets and signaling pathways differ." (PMID 40626312, 2025). "Nonetheless, it’s crucial to note that immunomodulators commonly used in IBD management, such as corticosteroids, aminosalicylates, methotrexate, anti-TNF-α, and other biologics, could increase the risk of opportunistic infections in the oral cavity." (PMID 37645044, 2023). "Although it has been suggested that the risk of opportunistic infections is increased with anti-TNF-α therapy, recent studies have shown that the risks have varied, while vedolizumab, for example, has not been associated with major infectious complications because of its primary gut selectivity." (PMID 35323234, 2022).